IGFBP2 (insulin like growth factor binding protein 2)
Diseases named in the same sentence as IGFBP2 in open-access papers (continued):
Sharing a sentence is not in itself a finding about the gene and the disease.
tumor (continued). "There are mixed reports on the role that IGFBP-2 plays in cancer progression, with some indicating a tumour suppressive role and others showing that IGFBP-2 may act as an oncogene." (PMID 31903164, 2019). "Finally, IGFBP2 is a tool for proliferation, apoptosis, and migration of cells during embryonic development and tumor cells." (PMID 30641895, 2019). "As the serum protein level of IGFBP2 was significantly increased in the orthotopic GL261 tumor bearing mice compared to the no tumor mice (** p < 0.01), we treated the mice with anti-IGFBP2 intraperitoneally after 7 days injection of tumor cells until the complete death of the control mice." (PMID 31560714, 2019). "Moreover, neutralizing antibodies against IGFBP2 impaired IGFBP2-mediated oncogenic signaling pathways and inhibited the spread of tumor cells." (PMID 31296788, 2019). "These preliminary data in vitro data suggest that the presence of IGFBP-2 in tumours may play a role in determining chemosensitivity." (PMID 31903164, 2019). "In GBM, IGFBP2 overexpression significantly increased the invasive capability of tumor cells." (PMID 31138764, 2019). "Taken together, these results demonstrated that MMP‐1 secreted by MSCs could efficiently cleave the IGF‐2/IGFBP2 complex, facilitating the migration of MSCs toward tumor cells via the IGF‐2/IGF‐1R signaling axis." (PMID 29321953, 2018). "One may speculate that patients with upregulated HIF-1 and IGFBP-2 pathways as a response to induction treatment have a tumor phenotype with maintained VEGF dependency and thus responsiveness to prolonged VEGF inhibition during maintenance." (PMID 30592740, 2018). "Our data demonstrated that MMP‐1 secreted by highly tumor‐tropic MSCs could act as IGFBP2 proteinase, resulting in cleavage of the IGF‐2/IGFBP2 complex followed by the extracellular release of free IGF‐2." (PMID 29321953, 2018). "But, there are several conflicting reports that IGFBP2 acts in a tumor suppressor role." (PMID 27901484, 2017). "Previously, it was recognized that IGF-II/IGFBP2 complex may partly bind to the extracellular matrix (ECM) from where IGF-II may be liberated by proteolysis, suggesting the role of IGFBP2 as a storage pool for IGF-II in the tumor microenvironment." (PMID 28036255, 2017). "Furthermore, we constructed an orthotopic tumor model to evaluate the role of IGFBP-2 on tumor metastasis in vivo." (PMID 28977895, 2017). "Moreover, knockdown of IGFBP-2 increased the anti-tumor properties of gemcitabine in the orthotopic tumor model." (PMID 28977895, 2017). "The IGFBP2 expression is elevated in many cancer types, in both tumor cells and plasma." (PMID 28931862, 2017). "IGFBP-2 also mediates tumor cell growth, invasion and resistance, while the mechanisms remain unclear." (PMID 28977895, 2017). "Our studies reveal a fourth resistance mechanism, in which cabozantinib induces the secretion of a spectrum of proteins, e.g. PAPPA and IGFBP2 that are known to increase tumorigenic properties of PCa cells, from osteoblasts to increase the survival and migration of tumor cells." (PMID 29088840, 2017). "Higher levels of HOTAIR and IGFBP2 were detected in the high-grade tumor area." (PMID 28931862, 2017). "Evidence elsewhere for an association between IGFBP-2 expression and BC progression remains contradictory with reports of association and non-association with overall survival or tumour progression." (PMID 27050076, 2016). "While studying by immunohistochemical methods the localization of IGFBP2 in human CRC tissue samples we detected an increased expression of IGFBP2 in the tumor tissue and an exclusive localization of IGFBP2 at the bottom of colonic crypts in the adjacent normal tissue." (PMID 27187476, 2016).
tumor (continued). "Our data show IGFBP2 as an inhibitor of the invasion process in our 3-D model of cervical pre-cancer and in the main, IGFBP2 tumour suppressive functions are those which antagonise IGF signalling, although IGF-independent pro-apoptotic functions of IGFBP2 have also been described." (PMID 26107517, 2015). "In addition to the variation of IGFBP2 expression between different tumors, there is also further variation of IGFBP2 expression levels, within an individual tumor." (PMID 25774149, 2015). "Additionally, real-time PCR analysis showed that IGFBP2 expression was higher among tumor specimens obtained from patients who had treatment-resistant EACs as compared with patients who had not yet received chemotherapy." (PMID 26317790, 2015). "Furthermore, the oxygenation of a tumor varies depending on blood supply to different regions of the tumor, hypoxia has been shown to regulate IGFBP2 expression and should also be considered when scoring IGFBP2 expression in tumor samples." (PMID 25774149, 2015). "In another such recent study, a novel approach has been used to develop protease resistant (PR) and protease resistant/non-matrix-binding (PR/NMB) variants of IGFBP-2 as potential tumour growth inhibitors." (PMID 25866791, 2015). "However, there are also inconsistent finding, which makes evaluation of IGFBP2’s oncogenic/tumor suppressive role difficult and also questions the suitability of IGFBP2 as a biomarker." (PMID 25774149, 2015). "However, there are a number of conflicting reports in vitro and in vivo where IGFBP2 acts in a tumor suppressor manner." (PMID 25774149, 2015). "Therefore, the observation that a protease-resistant IGFBP2 can suppress tumor growth creates the exciting opportunity to target proteases and potentially restore the suppressive actions of IGFBP2." (PMID 25774149, 2015). "For example, the elevated expression of the IGFBP2 protein observed in various cancers may represent a response to suppress tumor growth, mediated by IGFs; however, pro-tumorigenic proteases may ultimately inactivate this response." (PMID 25774149, 2015). "Reflecting on the cleaved status of IGFBP2 in cancer may also help to explain some of the contradictory evidence regarding its tumor suppressive/oncogenic role in carcinogenesis." (PMID 25774149, 2015). "Serum IGFBP-2 levels and tumor IGFBP-2 expression are dramatically elevated in a variety of human malignancies including GBM, and it has been reported that preoperative plasma IGFBP-2 levels are correlated with recurrence and disease-free survival in patients with GBM." (PMID 24690948, 2014). "Because IGFBP2 is a secretory protein, its increased expression in tumor tissues may be reflected in its concentrations in blood." (PMID 24069370, 2013). "To determine whether blood IGFBP2 levels reflect IGFBP2 expressions in patients’ primary tumors, we analyzed IGFBP2 expressions in two primary tumor tissues from patients with either high or low IGFBP2 in their blood samples." (PMID 24069370, 2013). "However, investigating on a larger set of patient samples with paired blood and tissue specimens will be required to determine the correlations between blood and tumor IGFBP2 levels." (PMID 24069370, 2013). "Thus, increased IGFBP-2 confers advantage or disadvantage for tumor growth, depending on cell type and physiological conditions." (PMID 23165420, 2013). "Therefore, prior to treatment, archival tumor tissue or fresh tumor biopsies were tested for the biomarker 1 (LRRC19 > IGFBP2) and/or biomarker 2 (PIK3CA mutant) to determine eligibility for the study in CLIA-approved space." (PMID 23342270, 2012). "To determine the cell types in which the proteins were differentially expressed, we performed immunohistochemical analyses for five molecules (ACC-pS79, CHK2, IGFBP2, cyclin B1, and caveolin 1) on samples that showed difference between normal and tumor tissues." (PMID 22348039, 2012).
tumor (continued). "Furthermore, a tumour-specific pathway is implicated, with negligible levels of IGFBP-5 and IGFBP-2 in normal breast epithelial cells[B6,39,40]." (PMID 15642160, 2005). "In addition, the increase in IGFBP2 expression was found to correlate positively with the levels of the serum tumor marker CA125." (PMID 15686601, 2005). "Nevertheless, one specific IGF-binding protein known to be produced in excess by some tumour types (e.g. colorectum, prostate) is IGFBP-2, and this may lead to some increase in circulating levels (which are much lower than those of IGF-I and IGFBP-3)." (PMID 14583772, 2003). "Additionally, while lower in global rankings, several genes including COL6A3 (extracellular matrix remodeling), FKBP5 (glucocorticoid signaling), IGFBP2 (tumor invasion and angiogenesis), and TPM2 (cytoskeletal stability) appeared prominently in local SHAP plots for specific cancer samples." (PMID 40941703, 2025). "We then tested whether inhibiting Igfbp2 signaling in aged mice could impact tumor growth." (PMID 39007351, 2024). "Only IGFBP-2 was associated with increased tumor grade but not stage." (PMID 38137390, 2023). "Additionally, IGFBP2 may enhance the tumor-promoting effects of immune cells, leading to increased inflammation, angiogenesis, and immunosuppression within the tumor microenvironment." (PMID 37928523, 2023). "Therefore, circVANGL1 is believed to act as a tumor promoter through IGFBP-2 upregulation." (PMID 35597813, 2022). "Therefore, this study will focus on the mechanism of IGFBP2's action as a tumor suppressor." (PMID 36159855, 2022). "Similarly, no other known clinical parameters, including gender, age, tumor size and site were found associated with IGFBP2 and anti-IGFBP2 antibodies levels." (PMID 32093404, 2020). "Anti-IGFBP2 decreased the tumor volume of GBM in mice brains (p = 0.0123) and improved the median survival of tumor-bearing mice compared to IgG control (median survival time: 39.0 days versus 93.4 days, p = 0.0198), suggesting that blocking IGFBP2 may have therapeutic effects on human GBM." (PMID 31560714, 2019). "Therefore, we hypothesized that it is possible that IGFBP2 comes from the tumor, and is one of the autocrined hormones." (PMID 29500455, 2018). "However, where the elevated IGFBP2 comes from and how to promote tumor progression?" (PMID 29500455, 2018). "Similarly, in activated Kras background, overexpression of IGFBP-2 promotes tumor growth." (PMID 26217584, 2015). "Interestingly, protease resistant IGFBP2 was also able to suppress tumor growth in vivo." (PMID 25774149, 2015). "Thus, it is important to consider whether these results demonstrate a correlation of IGFBP2 driving tumorigenesis or are, in fact, reflective of tumor stage/subtype." (PMID 25774149, 2015). "Also, we cannot measure the IGFBP-2 expression level in residual tumor after combined treatment." (PMID 24690948, 2014). "Secondly, elevated plasma IGFBP-2 may affect residual tumor tissue and promote tumor growth." (PMID 24690948, 2014). "Some of these genes/pathways may have a role in IGFBP2 mediated tumor progression." (PMID 23767917, 2013). "Notably, the expression of IGFBP2, known for its role in regulating cancer cell proliferation and metastasis, was significantly downregulated after combined treatment in H23 and A549 cells, which was also confirmed in A549- and H460-derived xenograft tumor models." (PMID 40935839, 2025). "Elevated expression for transcripts IGFBP2 and LGALS1 in cells at the tumor periphery (GBM-LE region) indicate aberrant ECM remodeling at the invasive GBM edge." (PMID 41366031, 2025). "IGFBP2 can be released from platelets upon activation, leading to the modulation of IGF signaling in the tumor microenvironment which suggests a role as a functional mediator as well as a biomarker for disease progression." (PMID 41226816, 2025).
tumor (continued). "HIF-1-induced overexpression of IGFBP-2 led to elevated PKM2 expression and a significant shift towards glycolysis, enabling tumor survival in hypoxic environments." (PMID 41226289, 2025). "Molecular markers: Alongside established TEP biomarkers (ITGA2B, IGFBP2), PSG2 indicates tumor-derived RNA uptake." (PMID 41226816, 2025). "Chemotherapy works in a defined manner and this study explores the role of a molecule called insulin-like growth factor binding protein-2 (IGFBP-2), frequently increased by tumours, in the response of cancer cells to chemotherapy." (PMID 38893232, 2024). "In vivo experiments using a GBM xenograft model substantiated the tumor-suppressive effects of SVIP, evident by suppressed tumor growth, decreased IGFBP-2 expression, and improved survival rates." (PMID 39138166, 2024). "Taken together, our findings suggest that the plasma IGFBP2 level is significantly elevated in PDAC and that this elevation and its extent are related to tumor progression, glucose metabolism, and prognosis." (PMID 39221034, 2024). "IGFBP2, part of the insulin-like growth factor binding protein (IGFBP) family, is involved in cell migration, tumor invasion, cell proliferation, and tumor angiogenesis." (PMID 39055656, 2024). "Together, IGFBP-2 and IGFBP-3 exemplify the complexity of IGF regulation in cancer biology, with their distinct roles contributing to the multifaceted nature of tumor development." (PMID 39585162, 2024). "Insulin-like growth factor binding protein 2 (IGFBP2) contributes to the activation of the STAT3 signaling pathway, leading to Treg differentiation and the creation of a suppressive tumor environment." (PMID 38902779, 2024). "To confirm the consistency of IGFBP-2 levels in plasma and tumors, we performed ELISA assays to measure plasma IGFBP-2 levels in both non-tumor and GBM patient groups." (PMID 39138166, 2024). "Overall, an inverse correlation was noted between tumor purity and the expression levels of IGF2BP3, EMP3, TUBA1C, AK2 and IGFBP2 (average PCC = −0.48)." (PMID 38171932, 2023). "In fact, a decreased production of fibronectin, IGF1 and IGFBP2 by haploinsufficient IGF1R fibroblasts, together with a downregulation of integrins expression in tumour cells, impaired the survival of tumour cells." (PMID 37033265, 2023). "Expression of IGFBP2 in pancreatic fluid, tissue, and plasma of PDAC patients is increased in correlation with tumor stage." (PMID 36712921, 2023). "The methylation of HOXA1, IGFBP2, PTX3, TIMP1, SHOX2, and SH2D4A decreases with increasing tumor grade." (PMID 37091145, 2023). "The secretion of IGFBP2 and CCL28 by miR-125bHigh altruists to induce tumor-wide chemorefractoriness is an oncogenic process, while cell cycle inhibition by high miR-125b expression in the altruists is a tumor suppressive event." (PMID 38093346, 2023). "We further demonstrated that IGFBP2 augmented IDO expression by activating STAT3 signaling in PDAC, thereby inducing Treg differentiation and promoting tumor progression." (PMID 36556226, 2022). "We further show that IGFBP2 augments IDO expression through the STAT3 signaling pathway in PDAC, thereby inducing Treg differentiation and tumor growth." (PMID 36556226, 2022). "During the pathological process, ADAMTS-1 can cleave or induce the release of proangiogenic factors (IGFBP2, HB-EGF, AR) and degrade ECM components, such as versican, to facilitate tumor invasion." (PMID 36338393, 2022). "Intrigued by our observation of IGFBP2 upregulation by DNA hypermethylation in two independent tumor cells lines (H3122 and MCF7), we continued exploring in greater detail the old MCF7 batch which showed the highest IGFBP2 mRNA upregulation." (PMID 34434494, 2021). "In the present study, we have also found that DNA methylation, which affects the levels of IGFBP2 expression, also unbalances BCL2 expression in two different tumor cell line models (HEK293T and MCF7)." (PMID 34434494, 2021).
tumor (continued). "And IGFBP2, EMP3, TIMP1 and SERPINE1 are all highly expressed in LGG tumor tissues compared with normal brain tissues." (PMID 32328202, 2020). "4T1 cells proliferated better in the presence of ASC.B6, however, adding recombinant IGFBP2 (rIGFBP2) to the cell culture, it resulted in significant decrease in ASC.B6 tumor-growth promoting effect." (PMID 32133294, 2020). "IGFBP2 was missing from ASC.B6 cells, and supplementation with a recombinant protein abolished tumor cell proliferation, and also mitigated the ASC.B6-induced Akt phosphorylation." (PMID 32133294, 2020). "In LGG tumor tissues, EMP3, IGFBP2, TIMP1 and SERPINE1 are all highly expressed, compared with normal brain tissues." (PMID 32328202, 2020). "Our results show that ASCs with altered genetic background promote tumor progression by unbalanced IGF1 and IGFBP2 secretion, which leads to enhanced growth of breast epithelial cells and favors tumorigenesis." (PMID 32133294, 2020). "According to the profiling results, radiation increased the exosomal connective tissue growth factor (CTGF) and insulin like growth factor binding protein 2 (IGFBP2) proteins, both of which were ascribed to favor tumor migration and progression." (PMID 33628730, 2020). "IGFBP-2 is the main IGFBP produced by prostate epithelial cells, and is increased in patients with prostate cancer, correlating with tumour stage and grade." (PMID 32056047, 2020). "We have previously demonstrated that secreted insulin-like growth factor binding protein 2 (IGFBP2) is overexpressed in RMS patients and correlates significantly with tumor stage and aggressiveness." (PMID 32093404, 2020). "IGFBP2 is the second most abundant IGF-binding protein (after IGFBP3), functions as a carrier for IGF-1 and likely promotes tumor progression through IGF-1R pathway." (PMID 31399589, 2019). "In this study we concentrated on the value of serological IGFBP2 to identify different tumor characteristics in NSCLC patients and the reversal effect of trichostatin A (TSA) on chemoresistance induced by high IGFBP2 expression." (PMID 29500455, 2018). "Considering the greater migratory capacity of tumor PaSCs when compared to normal PaSCs, the reduction in IGFBP-3 levels seems to overweigh the elevation of IGFBP-2, resulting in a net increase in the IGF-1 availability." (PMID 29475434, 2018). "In the present study, we further demonstrated that MMP‐1 secreted by the highly tumor‐tropic MSCs cleaved the IGF‐2/IGFBP2 complex that resulted in the release of free IGF‐2, which facilitated MSC migration toward tumor cells via the IGF‐2 signaling axis." (PMID 29321953, 2018). "Insulin-like growth factor binding protein 2 (IGFBP2) binds insulin, IGF1 and IGF2 in circulation, thereby modulating cell survival, migration, and invasion in neoplasms." (PMID 28410230, 2017). "To confirm the role of IGFBP2 in Hsp27-meditated tumor metastasis, we determined the levels of EMT biomarkers in IGFBP2-overexpressing and control Hsp27-KD cells." (PMID 28903396, 2017). "Angiogenesis also plays a crucial role in tumor malignancy and progression, and various angiogenesis-related genes and pathways, especially the EGFR/IGFBP2/HIF2αpathway, are upregulated in pHGGs." (PMID 26933822, 2016). "While IGFBP-2 is a known potent modulator of the mitogenic effects of IGFs, IGF-independent actions of IGFBP-2 have been recently recognized, suggesting that IGFBP-2 is a regulator of tumor growth and invasiveness in its own right." (PMID 24690948, 2014). "However, because the samples were from different sets of patients, it was not clear whether increased blood IGFBP2 was associated with increased IGFBP2 expression in tumor tissues, although such a correlation was observed in two paired samples." (PMID 24069370, 2013). "The protein profiles of nine targets, namely IGFBP2, IGF1, SHKBP1, ETS1, IL1α, STX2, MAML3, EGR3 and XIAP were verified as significant contributors to tumor classification." (PMID 24282616, 2013).